ACE (angiotensin I converting enzyme)
Diseases named in the same sentence as ACE in open-access papers (continued):
Sharing a sentence is not in itself a finding about the gene and the disease.
chronic obstructive pulmonary disease (116 papers, 2005 to 2025). A chronic and progressive lung disorder characterized by the loss of elasticity of the bronchial tree and the air sacs, destruction of the air sacs wall, thickening of the bronchial wall, and mucous accumulation in the bronchial tree. "For instance, in chronic obstructive pulmonary disease, the ACE I/D polymorphism was associated with high CRP levels." (PMID 37238156, 2023). "Increased ACE activity is caused by AngII and functional polymorphisms in the ACE gene, which increases vulnerability to asthma, pulmonary hypertension, and chronic obstructive pulmonary disease (COPD)." (PMID 37456637, 2023). "Recently, Sovari and colleagues demonstrated that, in a transgenic mouse model overexpressing cardiac angiotensin-converting enzyme (ACE 8/8 mice), c-Src tyrosine kinase inhibition prevents Cx43 loss, thus reducing susceptibility to cardiac arrhythmia." (PMID 24653841, 2014). "Many data indicate the association between ACE polymorphism, particularly the homozygote variant (Del/Del), might contribute to the risk of chronic obstructive pulmonary disease (COPD) and COPD with pulmonary hypertension among Asians." (PMID 35571459, 2022). "At present, the angiotensin‐converting enzyme (ACE) I/D polymorphism was considered to be associated to the pathogenesis of chronic obstructive pulmonary disease (COPD)." (PMID 39188047, 2024). "This research aimed to explore the ACE (insertion/deletion) gene association as key factor for chronic obstructive pulmonary disease (COPD) development in north Indian population." (PMID 32042834, 2019). "The relationship between polymorphism of the angiotensin I converting enzyme (ACE) gene and chronic obstructive pulmonary disease (COPD) has been examined in many previous studies." (PMID 27830153, 2016). "Certain anti-hypertensives (notably angiotensin-converting enzyme [ACE] inhibitors), some drugs used to treat cardiac arrhythmias, and most diuretics should be used with caution." (PMID 31328245, 2019). "Patients with chronic obstructive pulmonary disease, patients residing in the South, and black patients had a poorer adherence, while patients previously on ACE inhibitors/ARBs and patients initiated on maximum-dose sacubitril-valsartan had better adherence." (PMID 31772613, 2019). "Moreover, in a survey performed in 2019, 96 patients were undergone a research and it was demonstrated that the existence of D allele of the ACE gene may raise the risk for AH in patients with chronic obstructive pulmonary disease (COPD)." (PMID 37900914, 2023). "Moreover, the regulation factor of ACE expression, HIF-1α, is affected by aging and high-risk factors (diabetes, hypertension, and chronic obstructive pulmonary disease)." (PMID 37108839, 2023). "Common causes of CC include postnasal drip (upper airway cough syndrome), asthma, gastroesophageal reflux disease (GERD), infection of the respiratory system, chronic obstructive pulmonary disease (COPD), and angiotensin-converting enzyme (ACE) inhibitors." (PMID 35439945, 2022). "Common causes of chronic cough are side effects due to commonly used drugs (especially angiotensin converting enzyme [ACE] inhibitors), tracheo-broncomalacia, chronic obstructive pulmonary disease (COPD), bronchiectasis, asthma, obstructive sleep apnea, rhinosinusitis, and GERD." (PMID 32784573, 2020). "Furthermore, ACE-i may increase bradykinin levels, which in turn trigger norepinephrine release leading to higher susceptibility to cardiac arrhythmias." (PMID 24653841, 2014). "The most frequent causes of acute cough are viral or bacterial upper respiratory tract infections (URTIs), while those of chronic cough are asthma, gastro-esophageal reflux disease (GERD), chronic rhinitis, chronic bronchitis, chronic obstructive pulmonary disease (COPD), ACE-inhibitors treatment." (PMID 26097707, 2015).
chronic obstructive pulmonary disease (continued). "SD: standard deviation, BMI: body mass index, COPD: chronic obstructive pulmonary disease, LVEF: Left ventricular ejection fraction, ACE-i/ARB: angiotensin-converting enzyme inhibitor/angiotensin receptor blocker." (PMID 37090368, 2023). "ACE = angiotensin-converting enzyme; AT-II = angiotensin II; CAP = community-acquired pneumonia; CURB-65 = confusion, blood urea nitrogen, respiratory rate, blood pressure, age 65 or older; COPD = chronic obstructive pulmonary disease; qSOFA = quick sequential organ failure assessment score." (PMID 34424199, 2021).
essential hypertension (91 papers, 2005 to 2025). Hypertension that presents without an identifiable cause. "When scaled to represent SBP lowering achieved in clinical trials of ACE inhibitors for primary hypertension (equivalent to 8 mm Hg lower SBP), this represents an OR of 2.74 (95% CI 1.58 to 4.76)." (PMID 35113855, 2022). "In this study, we evaluated the influence of 3 months of angiotensin-converting enzyme (ACE) inhibition treatment on the morphological and functional arterial wall and cognitive performance changes in 30 newly diagnosed primary hypertensive patients." (PMID 31441902, 2019). "ACE-inhibitors are recommended as the drug of first choice in obese hypertensive adults, and in children with primary hypertension." (PMID 26940338, 2017). "Therefore, in this 3-month follow-up study, we aimed to evaluate the influence of ACE inhibitors on early morphological and functional changes of the arterial wall and cognitive performance impairments in newly diagnosed primary hypertensive patients." (PMID 31441902, 2019). "In this study, we identified and validated the surface proteins and enzymatic activity of chymase, angiotensin converting enzymes 1 (ACE) and 2 (ACE2), and neprilysin (NEP) in EVs isolated from the blood and urine of primary hypertensive patients." (PMID 39172521, 2024). "Another class of drugs affecting LOX-1 activity is the angiotensin-converting enzyme (ACE) inhibitors and AT1 receptor blockers, drugs that are commonly used in the treatment of primary hypertension." (PMID 38790688, 2024). "In a survey of North American pediatric nephrologists, 47 % chose angiotensin-converting enzyme (ACE) inhibitors; 37 %, calcium channel blockers, and 15 % diuretics as initial therapy in children with primary hypertension." (PMID 26746195, 2016). "Nevertheless, our findings may provide some insight into the lack of effectiveness of ACE inhibitors and ARB in the reduction of AF incidence in post hoc analyses of trials in patients with primary hypertension." (PMID 25626873, 2015).
hyperlipidemia (88 papers, 2007 to 2026). "Case of a 67 years-old woman with a clinical history of chronic ischemic heart disease and hyperlipidemia, in treatment with beta-blockers, ACE-inhibitors, antiplatelet agents and atorvastatin 20 mg/day for 10 years." (PMID 37147490, 2023). "Current smoking, hyperlipidemia and ACE I/D genotype were the significant variables in the univariate analysis; however, these parameters lost significance in multivariate analysis." (PMID 25161389, 2014). "Nonsurvivors less frequently had the following characteristics: hyperlipidemia, acute coronary syndrome, emergent coronary angiography or percutaneous coronary intervention before admission, angiotensin receptor blockers (ARBs) or angiotensin-converting enzyme (ACE) inhibitors, and beta-blockers." (PMID 38168588, 2024). "Moreover, the ACE activity of the atherosclerotic animal group A was found to be higher than in the control group C suggesting an activation of the endothelial cells under hyperlipidemia stress." (PMID 26628893, 2015). "This study has showed that treatment with statins in addition to a regimen with ACE inhibitors or ARBs can reduce proteinuria in patients with proteinuric CKD and hyperlipidemia." (PMID 26543646, 2015). "In conclusion, altogether our data show that postnatal early pharmacological inhibition of ACE modifies the development of WAT and hypothalamus, leading to hyperphagia, hyperlipidemia and overweight in adulthood." (PMID 25926796, 2015). "Therefore, we conclude that curcumin does not show ACE inhibitory effects, but has potential use as an alternative therapeutic compound to treat hyperlipidaemia." (PMID 27110504, 2016).
cardiomyopathy (84 papers, 2010 to 2026). A disease of the heart muscle or myocardium proper. "Based on these findings, the patient was diagnosed with DMD-associated cardiomyopathy, and optimal pharmacologic therapy, including an angiotensin-converting enzyme (ACE) inhibitor, a β-blocker, and a diuretic, was initiated." (PMID 41209090, 2026). "In studies validated with Hardy-Weinberg principle, there was an association between ACE I/D variants and cardiomyopathy risk under the recessive model, with a pooled OR of 0.779 (DD vs ID+II: 95% CI = 0.607–1.000; P = 0.050)." (PMID 38166133, 2024). "Twenty studies explored the association between ACE I/D gene polymorphism and the risk of cardiomyopathy." (PMID 38166133, 2024). "The ACE inhibitor perindopril is associated with a lower mortality in young DMD patients with cardiomyopathy." (PMID 37759719, 2023). "The primary finding in this single-center study is that only type of underlying cardiomyopathy and use of ACE-inhibitor respectively ARB had a significant impact on CRT-response in this subgroup." (PMID 33320290, 2021). "Only type of underlying cardiomyopathy and use of ACE-inhibitor had a significant influence on CRT-response with a favorable outcome of NICM compared to ICM." (PMID 33320290, 2021). "Angiotensin I converting enzyme (ACE) insertion/deletion (I/D) polymorphisms were found to be associated with cardiomyopathies." (PMID 23691019, 2013). "DMD-associated cardiomyopathy may be delayed and improved with steroids and cardioprotective therapies (e.g., ACE inhibitors, β-blockers, and mineralocorticoid receptor antagonists)." (PMID 39290213, 2024). "Several studies reported that ACE I/D polymorphism is associated with Cardiomyopathy." (PMID 38166133, 2024). "The ACE D allele has been related to the severity of cardiomyopathies of various etiologies." (PMID 39591456, 2024). "Secondly, previous literature has reported that the association between ACE D/I polymorphism and M235T polymorphism with cardiomyopathy may vary among different ethnicities." (PMID 38166133, 2024). "We evaluated the association of ACE I/D polymorphism with HF, performing acase-control study encompassing 343 patients with positive serology for CDstaged as non-cardiomyopathy (stage A; 100), mild (stage B1; 144), andsevere (stage C; 99) forms of Chagas heart disease." (PMID 32638886, 2020). "While standard therapies such as ACE inhibitors, SGLT2 inhibitors, and beta-blockers address clinical symptoms, their capacity to interrupt the underlying biochemical mechanisms of cardiomyopathy is often limited." (PMID 42193343, 2026). "Among clinically recommended therapies, ACE inhibitors and β-blockers have been adopted for managing radiation-related cardiomyopathy, mirroring standard heart failure protocols." (PMID 40831935, 2025). "Therapeutic strategies mirror standard cardiomyopathy management, incorporating ACE inhibitors, ARBs, aldosterone antagonists, and β-blockers." (PMID 40831935, 2025). "The treatment involves standard approaches for cardiomyopathy, including angiotensin-converting enzyme (ACE) inhibitors, beta-blockers, and diuretics." (PMID 38516462, 2024). "In this meta-analysis, we reviewed all eligible studies that evaluate the associations between ACE I/D, AGT M235T, and AGTR1 A1166C gene polymorphisms and the risk of cardiomyopathy." (PMID 38166133, 2024). "Angiotensin-converting enzyme (ACE) inhibitors are used clinically to control cardiomyopathy in patients with Duchenne muscular dystrophy." (PMID 38887391, 2024). "These limitations highlight the need for further research to explore the potential impact of different ethnicities and gene-environment interactions on the association between ACE D/I, AGTR1 A1166C, and M235T polymorphisms with cardiomyopathy." (PMID 38166133, 2024).
cardiomyopathy (continued). "The management of the first patient was complicated by several factors, including an early onset of cardiomyopathy, intolerance to ACE inhibitors, and untreated scoliosis, which hindered the implantation of a cardioverter defibrillator (ICD)." (PMID 40729215, 2024). "The DMD care guidelines 2018 suggested the use of CMRI for early detection of DMD-related cardiomyopathy and initiation of angiotensin-converting enzyme (ACE) inhibitors in boys > 10 years of age or those who have cardiac dysfunction in the investigations." (PMID 35359887, 2022). "Cardiac complications were observed in three (4.5%) patients who developed cardiomyopathy, two of which required ACE inhibitors." (PMID 36071886, 2022). "The current standard of care recommended by the DMD Care Considerations Working Group to delay the onset of cardiomyopathy includes the use of angiotensin-converting enzyme (ACE) inhibitors (i.e., Perindopril) by 10 years of age." (PMID 35340200, 2022). "In DMD patients, the first-line pharmacological management or prophylaxis treatment for cardiomyopathy includes angiotensin-converting enzyme (ACE) inhibitors or angiotensin receptor blockers (ARBs)." (PMID 33681102, 2021). "Treatment with ACE inhibitors has also been shown to impact the clinical course of DMD by delaying the onset of cardiomyopathy; however, the use of ACE inhibitors remains variable." (PMID 34022943, 2021). "Only cardiomyopathy type and use of Angiotensin-converting-enzyme (ACE) inhibitor had an impact on response to CRT-upgrade in a linear regression model." (PMID 33320290, 2021). "In a linear regression model, only cardiomyopathy type and use of ACE inhibitor respectively Angiotensin II receptor blockers (ARB) had an impact on response to CRT-upgrade." (PMID 33320290, 2021). "This study is very important for the cardiomyopathy in DMD children to preserve their myocardial function with medical treatment including ACE inhibitors, beta-blocker, diuretics, and inotropic agents." (PMID 33266491, 2020). "In patients with cardiomyopathy, ACE inhibitors and beta-blockers remain the cornerstone drugs used in practice, sometimes associated with mineralocorticoid receptor antagonists." (PMID 29304097, 2018). "The renin-angiotensin system (RAS) plays an important role in the pathophysiology of doxorubicin-induced cardiomyopathy, and the inhibition of ACE/AngII/AngII type 1 (AT1) receptor (AT1R) axis has been shown to improve doxorubicin-induced cardiomyopathy." (PMID 28445944, 2017). "Angiotensin-converting enzyme (ACE) inhibitors and loop diuretics can be used for cardiomyopathy." (PMID 38883129, 2024). "ACE gene variants have been associated with poor echocardiographic outcomes in cardiomyopathies, risk of HF, and mortality, regardless of the etiology of the heart disease." (PMID 39591456, 2024). "In this study, we conducted a systematic review and meta-analysis to summarize the findings regarding the impact of angiotensin converting enzyme (ACE) I/D, angiotensinogen (AGT) M235T, and angiotensin II Type 1 receptor (AGTR1) A1166C gene polymorphisms in patients with cardiomyopathy." (PMID 38166133, 2024). "The three most useful classes of drugs for reversing cardiac remodeling related to cardiomyopathy are angiotensin-converting enzyme (ACE) inhibitors or angiotensin-receptor blockers (ARBs), beta-adrenergic receptor blockers, and mineralocorticoid receptor antagonists (MRAs)." (PMID 35093159, 2022). "Consensus recommendation: Patients should continue taking ACE inhibitors or ARBs as treatment or prophylaxis for cardiomyopathy as their benefits outweigh the unknown risks of COVID-19." (PMID 33681102, 2021). "Similarly, it has been found that the combination of ACE inhibitors or angiotensin receptor antagonists with beta-blockers improves the outcome of patients with established cardiomyopathy." (PMID 33330280, 2020).
cardiomyopathy (continued). "Alternatively, retrospective analysis of clinical records or health claim records may provide preliminary evidence for the translation potential of currently used medications (for example the use of ACE inhibitors for cardiomyopathy in patients suffering from comorbid depression)." (PMID 39273628, 2024). "Angiotensin converting enzyme (ACE) inhibitors, angiotensin receptor blockers (ARB), and beta blockers should be used presymptomatically to prevent cardiomyopathy in DMD patients." (PMID 35935842, 2022). "In this study, the D2-mdx mouse model was characterized and tested to determine whether the ACE inhibitor Perindopril, already in clinical use, and Debio-025, a specific mPTP blocker with a human safety profile, either alone or in combination could have an impact on the extent of cardiomyopathy." (PMID 35340200, 2022). "In the context of DMD a number of open studies indicated that ACE inhibitors, angiotensin receptor blockers, beta-blockers and/or aldosterone antagonists might improve or preserve left ventricular systolic function and may delay the progression of cardiomyopathy." (PMID 31077250, 2019). "These disorders are categorized into major clinical groups, such as Skeletal Dysplasias (e.g., analysis of genes like ACAN, ACP5, and ACVR1), Osteogenesis Imperfecta (COL1A1, COL1A2, BMP1), Metabolic Disorders (ACE, AGT, BICC1), and Cardiomyopathies, among others." (PMID 40282387, 2025). "Studies using neurohormonal antagonists drugs such as Angiotensin-converting enzyme (ACE) inhibitors or Angiotensin receptor blockers (ARB), beta-blockers, and others have been successful or unsuccessful in preventing doxorubicin-induced cardiomyopathy." (PMID 38385137, 2024). "While ACE inhibitors are used with or without beta blockers for cardiomyopathy in muscular dystrophy patients, congestive heart failure is treated with diuretics and oxygen." (PMID 37759719, 2023). "As there is no specific therapy for PLN-R14del-related cardiomyopathy, current HF guidelines, which recommend treatment with angiotensin-converting enzyme (ACE) inhibitors, beta-blockers and MRAs or a combination, are applied for treatment." (PMID 32555305, 2020). "This randomized, double-blinded and placebo-controlled trial investigated the effect of a combined ACE-inhibitor and beta-blocker treatment on the progression to DMD-related cardiomyopathy in boys with preserved left ventricular function and between 10 and 14 years of age." (PMID 31077250, 2019). "Our analysis of initiation of a combined therapy with the ACE-inhibitor enalapril and the β-blocker metoprolol in DMD patients younger than 14 years of age and with preserved left ventricular function is suggestive to delay the progression of the intrinsic cardiomyopathy to left ventricular failure." (PMID 31077250, 2019). "Cardiomyopathy is a major contributor of death amongst DMD patients, and, therefore, multiple approaches have been implemented to treat the cardiac phenotype, including corticosteroids, beta-blockers, angiotensin converting enzyme (ACE) inhibitors and antimineralocorticoid diuretics." (PMID 30281092, 2019). "Three further studies implicated that the use of ACE inhibitor or eplerenone treatment may attenuate, but not prevent, the deterioration of LV systolic function, which is typically observed in DMD cardiomyopathy." (PMID 31077250, 2019). "In patients with chemotherapy-induced cardiomyopathy, those treated with a combination of ACE-inhibitor (ACEi) and BB had significant improvement in LVEF (26% ± 10.20% versus 37% ± 17.6%, p = 0.028), which was not seen with Angiotensin converting enzyme inhibitor (ACEi) treatment alone." (PMID 36158986, 2022).